LGALS3 (galectin 3)
Diseases named in the same sentence as LGALS3 in open-access papers (continued):
Sharing a sentence is not in itself a finding about the gene and the disease.
colon carcinoma (continued). "A series of analyses were conducted in this study and showed that alteration of C1GalT1 expression in human colon cancer cells reciprocally changes tumour cell-cell and tumour-macrophage interactions mediated by galectin-3 and MGL with significant impact on tumour growth and progression." (PMID 37612278, 2023). "Similarly, as demonstrated in colon cancer cells, an increase in terminal α2,6-sialylation on β1-integrins blocks their binding to extracellular galectin-3, inhibiting galectin-3-mediated apoptosis." (PMID 35205768, 2022). "Since both studied pectins induced apoptosis in colon cancer cells, it was also checked whether they could affect the cellular amount of galectin-3 (Gal-3)." (PMID 35745651, 2022). "Recently, we found that galectin-3 (Gal-3) highly expressed on the cell membrane of drug-resistant colon cancer cells, and modified citrus pectin (MCP) could selectively bind with Gal-3." (PMID 34789268, 2021). "Blocking galectin 3 reduced COX-2 induction in colon cancer cells significantly." (PMID 30305116, 2018). "Therefore, we explored the association between galectin-3 and CEA and their potential role in metastasis of colon cancer in this study." (PMID 28977916, 2017). "Collectively, inhibition of galectin-3/β-catenin signaling pathway via post-transcriptional control by siHuR may provide a powerful regimen for reversing MDR in colon cancer." (PMID 28968471, 2017). "In the co-culture experiments, we demonstrated that galectin-3 mediated the promoter effects of AD-MSCs on colon cancer cell proliferation to some extent, as specific knockdown of galectin-3 with siRNA significantly reversed the MSC-mediated stimulation of colon cancer cell growth." (PMID 26273429, 2015). "Senescent MSCs may alter the tissue microenvironment and affect nearby malignant cells via cytokine secretion, and galectin-3 is an important mediator of senescent AD-MSC–mediated stimulation of colon cancer cell growth." (PMID 26273429, 2015). "Galectin-3 is also known to maintain epidermal growth factor receptor lattice formation on colon cancer cells for enhancing growth and epithelial mesenchymal transition that is implicated in cancer stem cells formation, resulting in the progression, and metastasis." (PMID 26448934, 2015). "On the other hand, the binding of extracellular galectin-3 to N-glycans on desmoglein, a cadherin present on desmosomes, seems to promote the stability of cadherin at the cell surface and in epithelial intercellular adhesion on colon cancer cells." (PMID 24982845, 2014). "In the present study, colon cancers as a group had low galectin-3 levels, though its contribution to progression is unknown." (PMID 22039439, 2011). "The results published regarding expression of galectin-3 in colon cancer are conflicting." (PMID 23658855, 2010). "Aside from facilitating adhesion, galectin 3 is strongly involved in inflammatory processes and mRNA expression has been observed in IELs from patients with Crohn's disease and bowel information, colon carcinoma and colitis." (PMID 19500416, 2009). "Hence, they speculated that the relative ratio between LGALS3BP and galectin-3 secreted by colon cancer cells in vivo may play an important role during colon cancer progression and metastasis by modulating tumor cell adhesion." (PMID 34565385, 2021). "In summary, our study suggests that senescent MSCs may alter the tissue microenvironment and affect nearby malignant cells via cytokine secretion, and that galectin-3 is an important mediator of senescent AD-MSC–mediated stimulation of colon cancer cell growth." (PMID 26273429, 2015). "However, the role of galectin-3 in colon cancer drug resistance is complex and unclear." (PMID 24303084, 2013). "GAL has shown affinity for receptors such as the pro-metastatic protein galectin-3 (GAL-3), and GAL-3 is overexpressed in colon cancer, so GAL is a valid clue for improving the affinity of NGs to colon cancer cells." (PMID 41590049, 2025).
colon carcinoma (continued). "Extracellular galectin-3 interacts with the EGFR and increases EGFR phosphorylation and activation, resulting in colon cancer cell migration." (PMID 36823664, 2023). "Galectin-3 potentiates cell migration and metastasis through activation of the K-RAS–RAF-Erk1/2 pathway in colon cancer." (PMID 36873388, 2023). "In this way, overexpression of ST6GalT-1 and α2,6-sialylation of β1 integrins prevents galectin-3 (Gal-3) binding and pro-apoptotic activity in SW48 colon cancer cells." (PMID 29416702, 2018). "We set sights on increasing the chemosensitivity of colon cancer cells to Epi through suppression of MDR transporters and apoptosis induction via inhibition of HuR-mediated galectin-3/β-catenin pathway." (PMID 28968471, 2017). "Our results showed that siHuR decreased transcriptional expressions of galectin-3, β-catenin, cyclin D1, Bcl-2, P-gp, MRP1, and MRP2 in epirubicin-treated colon cancer cells." (PMID 28968471, 2017). "Western blot analysis revealed that galectin-3 was expressed in both cell lysates and supernatants of DLD1 and Caco2 colon cancer cells." (PMID 28977916, 2017). "This is a pioneer study correlating the knockdown and overexpression of galectin-3 with ABC transporter modulation and apoptosis regulation in colon cancer cells with the MDR spectrum." (PMID 24303084, 2013). "Furthermore, galectin-3 mediates the Wnt signaling pathway and nuclear β-catenin accumulation by regulating glycogen synthase kinase-3β (GSK3B) activity in human colon cancer cells." (PMID 37185758, 2023). "Interestingly, it has been shown that Galectin-3 (GAL-3) is a ligand for oncofetal Thomson-Friedenreich carbohydrate (Galβ1, 3GalNAcα-, T, or TF) antigens on MUC1 mucin, which are expressed on human colon cancer cells." (PMID 30405607, 2018). "Binding between GPVI and galectin 3 together with PDGF initiated a cyclooxygenase-2 (COX-2) upregulation and stabilization in colon cancer cells and finally a release of increased PGE2 levels from tumor cells with a maximum after 20 h of platelet tumor cell interaction." (PMID 30305116, 2018). "Previous reports have shown that galectin-3 mediates nuclear β-catenin accumulation and subsequently increases TCF4 transcriptional activity followed by the upregulation of its target genes, such as cyclin D1 and c-myc, in colon cancer cells." (PMID 24303084, 2013). "We show for the first time that the silencing of galectin-3 sensitizes MDR cells to epirubicin by inhibiting ABC transporters and activating the mitochondrial pathway of apoptosis through modulation of the β-catenin/GSK-3β pathway in human colon cancer cells." (PMID 24303084, 2013). "In our previous study, we showed for the first time that the treatment of siRNA against galectin-3 sensitized MDR cells to Epi by inhibiting P-gp and MRPs and the activation of the mitochondrial apoptosis pathway through modulation of the β-catenin/GSK-3β pathway in human colon cancer Caco-2 cells." (PMID 28968471, 2017). "In conclusion, we show for the first time that galectin-3 silencing sensitizes MDR cells to epirubicin by inhibiting P-gp and MRPs and the activation of the mitochondrial apoptosis pathway through modulation of the β-catenin/GSK-3β pathway in human colon cancer cells." (PMID 24303084, 2013). "To further determine the relationship between galectin-3 expression and protease secretion, we separated the heterogenous HT29 colon cancer cells into invasive and none-invasive sub-populations by culturing the cells in trans-wells." (PMID 37055381, 2023). "Another study suggests that polysaccharides with content of RG-I and HG variation could inhibit colon cancer cells proliferation by decreasing ICAM1 expression, a protein responsible for cell–cell interaction and cell–ECM interaction independent of galectin-3 expression." (PMID 29185464, 2017).
Insulin resistance (73 papers, 2013 to 2025). Increased resistance towards insulin, that is, diminished effectiveness of insulin in reducing blood glucose levels. "Several studies have previously found associations between galectin-3 and insulin resistance markers in experimental studies in animal models." (PMID 38777863, 2024). "Insulin resistance, left ventricular hypertrophy and circulating levels of galectin-3 were associated with a worsening of the diastolic function in morbidly obese patients." (PMID 36362577, 2022). "There is an underlying association between galectin-3 and insulin resistance in that galectin-3 directly binds the insulin receptor, which inhibits downstream insulin receptor signaling." (PMID 35008499, 2021). "Galectin-3 reportedly participates in the inflammatory process that causes insulin resistance in the target tissues." (PMID 34444962, 2021). "Recently, galectin-3 has been associated with biomarkers of β-cell dysfunction and thus has been proposed to play a more prominent role in insulin secretion than in insulin resistance due to a pro-fibrotic mechanism." (PMID 32294902, 2020). "We investigated the association between serum galectin-3 and insulin resistance in patients with type 2 diabetes using a glucose clamp method." (PMID 25302080, 2014). "Our results suggest that low levels of serum galectin-3 are associated with insulin resistance in patients with type 2 diabetes." (PMID 25302080, 2014). "Galectin-3-deficient mice have been shown to exhibit excess adiposity, hyperglycemia, insulin resistance and systemic inflammation." (PMID 25302080, 2014). "Galectin-3 binds to the insulin receptor and causes insulin resistance." (PMID 37738450, 2024). "In our article, we focused only on selected ones—nesfatin-1, preptin, myonectin, omentin-1, gremlin-1, galectin-3, neuregulin-4, xenopsin-related peptide, xenin, neudesin, and lipocalin-2—and investigated their associations with insulin resistance in patients with PCOS." (PMID 35206286, 2022). "Furthermore, AnxA2 interacts with galectin-3 at the cell surface, which directly induces cellular insulin resistance and associated inflammation under obese conditions by impairing insulin signaling." (PMID 34681689, 2021). "It was speculated that this may be associated with galectin-3 and insulin resistance in GDM, but further research is required to investigate this observation." (PMID 35008499, 2021). "Of note, Galectin 3 (LGALS3) has been reported to cause insulin resistance." (PMID 31950067, 2019). "The results of galectin-3 in T2DM seems confusing because some studies claim that galectin-3 deficiency is associated with insulin resistance, and galectin-3 elicits a protective effect in T2DM by acting as a receptor for advanced glycation end products (AGEs)." (PMID 31109008, 2019). "Therefore, we hypothesize that low serum galectin-3 could be associated with insulin resistance and beta cell function in patients with type 2 diabetes." (PMID 25302080, 2014). "Although galectin-3 has been explored in numerous conditions, scientific information on the relationship between malaria-related insulin resistance and circulating galectin-3 levels is limited." (PMID 40802820, 2025). "Galectin-3 is involved in the development of insulin resistance through direct interactions with the insulin receptor, with altered insulin-regulated glucose metabolism in adipocytes, myocytes and hepatocytes." (PMID 38777863, 2024). "Within this context, galectin-3 emerges as a biomarker of interest, offering insights into the complex interactions between insulin resistance, chronic inflammation, and PCOS." (PMID 39958874, 2024). "This insight opens up new avenues for research into the pharmacodynamics of metformin in patients with PCOS and its interaction with galectin-3, a marker that has been increasingly recognized for its role in inflammatory processes and insulin resistance." (PMID 39958874, 2024).
Insulin resistance (continued). "By reducing oxidative stress and enhancing mitochondrial efficiency, metformin lowers inflammation and insulin resistance, key contributors to galectin-3 overexpression." (PMID 39958874, 2024). "In particular, the authors observed that isoquercetin can enhance insulin resistance by suppressing galectin-3." (PMID 39770043, 2024). "Galectin-3 has been implicated in mTORC1 signaling, particularly in cellular metabolism and its compartmentalization in lysosomes, suggesting that the suppression of this pathway by metformin could reduce galectin-3 expression, thereby alleviating insulin resistance and chronic inflammation in PCOS." (PMID 39958874, 2024). "Galectin-3 has been found to bind directly to insulin receptors and inhibit downstream cellular pathways, with resultant insulin resistance in multiple organs and related complications." (PMID 37240626, 2023). "The homeostasis model assessment (HOMA)—insulin resistance (IR) index was also increased in Lgals3−/− versus wild type mice and the euglycemic-hyperinsulinemic clamp confirmed the lower whole-body insulin sensitivity in the Lgals3−/− animals." (PMID 33208796, 2020). "Recent studies have clearly shown that soluble galectin 3 strongly influences the development of insulin resistance." (PMID 32117058, 2020). "Since galectin-3 interaction with the insulin receptor has been identified as a mechanism of insulin resistance, these findings support an additional mechanism by which carrageenan exposure can impair insulin signaling." (PMID 32377523, 2020). "This study showed that Galectin-3 (Gal3), an inflammatory cytokine secreted by macrophages, can bind to insulin receptors and interfere with related signaling pathways, resulting in insulin resistance." (PMID 28758131, 2017). "This last study strongly supports the use of galectin-3 inhibitors as a new approach to treat obesity-related insulin resistance and its comorbidities." (PMID 28115795, 2017). "The authors showed that a small inhibitor of galectin-3 reduced insulin resistance in HFD mice by improving insulin sensitivity in myocytes and hepatocytes." (PMID 28115795, 2017). "We also found a correlation between serum galectin-3 levels and insulin resistance, implicating this molecule as a potential biomarker of diabetic vasculopathy." (PMID 26047815, 2015). "Our study indicates that low levels of serum galectin-3 in patients with type 2 diabetes have insulin resistance and hyperinsulinemia similar to galectin-3 knockout mice." (PMID 25302080, 2014). "This study indicates that low serum galectin-3 concentrations strongly correlates with insulin resistance and hyperinsulinemia, evaluated by glucose clamp method, HOMA-IR, and ISI." (PMID 25302080, 2014). "Given the role of galectin-3 in driving both insulin resistance and inflammatory processes, targeting this pathway may offer new strategies for improving both metabolic and reproductive outcomes in women with PCOS." (PMID 39958874, 2024). "Plasma galectin-3 was associated with TyG-index, but not with any other marker of insulin resistance." (PMID 38777863, 2024). "Moreover, palmitic acid can also induce insulin resistance of macrophages in vitro by upregulating galectin-3 (Gal-3) expression and promoting the TLR4/phosphorylated-NF-B signaling pathway." (PMID 36355546, 2022). "Galectin 3 appears to be important for the development of insulin resistance in target tissues." (PMID 32117058, 2020). "This is to some degree in line with results from an animal model showing that GALECTIN 3 deficiency mice fed on a high fat diet develop increased VAT and increased fasting glucose, HbA1c and insulin resistance, indicating GALECTIN 3 to be protective against T2DM and obesity." (PMID 32820223, 2020). "Besides, we also observed a potential role for galectin-3 in hepatocyte, adipocyte, and myocyte insulin resistance, suggesting that galectin-3 can link inflammation to decreased insulin sensitivity." (PMID 31080833, 2019).
Insulin resistance (continued). "Based on previous literature and our study results, galectin-3 inhibitor play a role in mediating inflammatory pathways and platelet activation and might benefit the groups of insulin resistance." (PMID 31080833, 2019). "As the multiple regression analysis shows, we consider that galectin-3 is associated with insulin resistance rather than insulin secretion in patients with type 2 diabetes." (PMID 25302080, 2014). "Therefore, the current study examined the association between galectin-3 and insulin resistance in diabetic and non-diabetic adults with or without malaria at the Tema General Hospital." (PMID 40802820, 2025). "This implies that galectin-3 is not linearly associated with insulin resistance in our context." (PMID 40802820, 2025). "Furthermore, galectin-3 (gal-3) is a member of the galectin family that induces insulin resistance." (PMID 36230963, 2022). "Hence, increased ARSB activity may lead to a decline in serum galectin-3 and to reduced insulin resistance." (PMID 32377523, 2020). "Inhibition of galectin-3 could be a new approach to treat insulin resistance." (PMID 31080833, 2019). "Furthermore, the results of this study also provided preliminary evidence that extracellular galectin-3 binds to the insulin receptor directly and attenuates downstream pathways, suggesting galectin-3 to be a novel targetable link between the insulin resistance and T2DM." (PMID 31109008, 2019). "Galectin-3 levels correlated significantly with the glucose disposal rate (R = 0.71, P < 0.001), fasting insulin (R = −0.56, P < 0.01), homeostasis model assessment for insulin resistance (R = −0.52, P < 0.05), and the insulin sensitivity index (R = 0.62, P < 0.005)." (PMID 25302080, 2014). "Galectin-3 could not associate with insulin resistance in our context." (PMID 40802820, 2025). "In the current study, circulating galectin-3 level tended to be higher in diabetics compared with non-diabetic controls without malaria in support of previous studies but at variance with a Japanese study that rather associated low galectin-3 level with insulin resistance." (PMID 40802820, 2025). "Previously, galectin-3 was shown to bind less to chondroitin 4-sulfate when ARSB was reduced, and to bind with the insulin receptor and contribute to insulin resistance." (PMID 32377523, 2020). "In this study, the relationship between galectin-3 and insulin resistance was investigated in diabetic and non-diabetic participants with or without malaria receiving treatment at the TGH." (PMID 40802820, 2025). "Moreover, it is hypothesized that galectin-3, mainly derived from macrophages and the adipokine adiponectin, might promisingly participate in the “cross-talk” of macrophages and adipocytes, serving as a new diabetic target by functioning together with insulin resistance and inflammation." (PMID 34096884, 2021). "It was suggested that there is a possible contribution of galectin-3 to GDM that mostly involved pathways in insulin resistance and not insulin secretion." (PMID 35008499, 2021). "However, a greater reduction in phosphorylated AKT levels was observed in aortic tissue lysates from Lgals3 (−/−) mice after HFD, indicating the onset of vascular insulin resistance." (PMID 26047815, 2015). "However, in our context, results from the regression analyses did not identify galectin-3 as an independent predictor of insulin resistance." (PMID 40802820, 2025). "Therefore, this cross-sectional study was designed to examine the linear relationship between galectin-3 and malaria-related insulin resistance in diabetic and non-diabetic Ghanaians receiving treatment at the Tema General Hospital (TGH)." (PMID 40802820, 2025). "Although the risk of insulin resistance is known to increase with age, in the current study, a negative correlation was rather observed between age and HOMA-IR, WHR, HDL and insulin but positive with galectin-3 in respondents with T2DM without malaria." (PMID 40802820, 2025).